PRC1 (protein regulator of cytokinesis 1)
Diseases named in the same sentence as PRC1 in open-access papers (continued):
Sharing a sentence is not in itself a finding about the gene and the disease.
dementia (1 paper, 2019). Loss of intellectual abilities interfering with an individual's social and occupational functions. "Genes near all DMRs were enriched for functions in abnormal B cell physiology, while those near regions hypomethylated in WDH were enriched for functions in dementia, mental deterioration, and for belonging to the chromatin-modifying polycomb repressive complex 1 (PRC1)." (PMID 30709419, 2019).
development (1 paper, 2024). "Dysfunctional PRC1 induced a follicle development disorder in a time-dependent manner attributed to the arrested transition of primary-to-secondary follicles." (PMID 38389850, 2024).
endometrial cancer (1 paper, 2015). Primary or metastatic malignant neoplasm involving the endometrium (mucous membrane that lines the endometrial cavity). "A recent report that investigated the expression of CBX2 in human cancers showed initial evidence of an oncogenic role; however, the overexpression of both CBX2 and EZH2 in the basal-like subgroup indicates the importance of interplay between PRC1 and PRC2 in endometrial cancer." (PMID 26431491, 2015).
Fanconi anemia (1 paper, 2022). Fanconi anemia (FA) is a hereditary DNA repair disorder characterized by progressive pancytopenia with bone marrow failure, variable congenital malformations and predisposition to develop hematological or solid tumors. "Consistently, function analysis in our study also revealed the possible regulation of the Fanconi anemia pathway by PRC1." (PMID 35983074, 2022).
fibrosarcoma (1 paper, 2021). A malignant mesenchymal fibroblastic neoplasm affecting the soft tissue and bone. "Induction of the 8p human XIST cDNA transgene in the HT1080 fibrosarcoma cell line has been shown to recruit the PRC1/2 established histone marks, ubH2A and H3K27me3." (PMID 33750950, 2021).
gastric tumor (1 paper, 2022). "Since the RHOA mutation can lead to the fatty acids production in TME by gastric tumor cells, we speculate that in the TME of LIHC, maybethe upregulated PRC1 recruits Tregs by regulating RHOA and its RHO family." (PMID 35983074, 2022).
head and neck squamous cell carcinoma (1 paper, 2021). A squamous cell carcinoma that arises from any of the following anatomic sites: lip and oral cavity, nasal cavity, paranasal sinuses, pharynx, larynx, and salivary glands. "For example, it was shown that BMI1, a component of PRC1, acted cooperatively with TWIST1, one of EMT-related transcription factors (EMT-TFs), to repress CDH1 during EMT in head and neck squamous cell carcinoma." (PMID 33779563, 2021).
hepatitis C (1 paper, 2024). "Thus, elucidating the mechanism by which HCV infection can regulate PRC1 activity to regulate genes other than HOX genes is important for clarifying the molecular mechanism of hepatitis C pathogenesis and for the development of therapies for hepatitis C." (PMID 39329491, 2024).
intellectual disabilities (1 paper, 2017). "AUTS2 codes for a chromatin-remodeling protein that functions as a component of the polycomb repressive complex 1 (PRC1); loss of function mutations can lead to ASD, SZ and intellectual disabilities." (PMID 28321286, 2017).
ischemic stroke (1 paper, 2021). A stroke disorder caused by obstruction of blood flow to the brain, due to thrombotic (local blood clot formation) or embolic (due to a blood clot or other material traveling from another site) event. "Prc1 is also involved in cell proliferation, causing an abnormal cell cycle, and the Prc1-mediated cascade pathway is also associated with neuronal necrosis in ischemic stroke." (PMID 34566862, 2021). "Finally, comprehensive analysis of the results identified the miR-425-5p-Cdk1, mmu-miR-1186b-Prc1, mmu-miR-434-3p-Prc1, and mmu-miR-453-Prc1 miRNA–mRNA networks as key networks that are regulated by EA and linked to ischemic stroke." (PMID 34566862, 2021). "Ultimately, seven downregulated hub genes (including Mki67, Cdk1, Tpx2, Cenpf, Ccnb2, Prc1, and Top2a) were identified as key genes regulated by EA treatment in ischemic stroke by PCR validation." (PMID 34566862, 2021). "Overall, key miRNA-mRNA networks were identified based on RNA-seq and RT-qPCR validations, and we found that miR-425-5p-Cdk1, mmu-miR-1186b-Prc1, mmu-miR-434-3p- Prc1, and mmu-miR-453-Prc1 were crucial networks regulated by EA in brain neuronal cells of ischemic stroke." (PMID 34566862, 2021).
kidney cancer (1 paper, 2025). Primary or metastatic malignant neoplasm involving the kidney. "Additionally, immunohistochemical analysis of kidney cancer and adjacent tissues from NJMU ccRCC cohort indicated absent PRC1 expression in normal controls, while moderate expression was observed in ccRCC tissues, further underscoring PRC1's importance in renal cancer pathogenesis." (PMID 40093809, 2025).
lipoma (1 paper, 2024). A benign, usually painless, well-circumscribed lipomatous tumor composed of adipose tissue. "In addition to known RITA partners, such as RBP-J (recombination signal binding protein for immunoglobulin kappa J region) and LPP (lipoma-preferred partner), PRC1, NUMA1 (nuclear mitotic apparatus protein 1) and MAP1B (microtubule-associated protein 1B) were among the RITA interaction partners." (PMID 39839673, 2024).
microcephaly (1 paper, 2021). A congenital or acquired developmental disorder in which the circumference of the head is smaller than normal for the person's age and sex. "For example, mutations in the PRC1 interactor AUTS2 have been shown to cause an autosomal dominant form of syndromic mental retardation, including comorbidities such as ID, ASD, microcephaly, short stature and cerebral palsy." (PMID 33263776, 2021). "Although for PRC1 no dominant germline mutations have been described, autosomal recessive mutations in the PRC1 complex protein PHC1 have been shown to cause a form of microcephaly with short stature in two Saudi siblings." (PMID 33263776, 2021).
myelogenous leukaemia (1 paper, 2019). "In one study, using myelogenous leukaemia cell line K562 and normal fibroblasts Hs68, ChIP-seq data for RING1B and H3K27me3 were used to assess the differences in global distribution of PRC1 and PRC2 in differentiated cells." (PMID 30649516, 2019).
Oral leukoplakia (1 paper, 2018). A thickened white patch on the oral mucosa that cannot be rubbed off. "Firstly, we evaluated the expression of PRC1 in 24 oral leukoplakia (OLK) and 54 OSCC specimens, which represent different clinicopathologic stages." (PMID 29752448, 2018).
oral squamous cell carcinoma (1 paper, 2018). "Accordingly, we speculate that PRC1 might regulate tumor progression in oral squamous cell carcinoma (OSCC)." (PMID 29752448, 2018).
pancreatitis (1 paper, 2016). Inflammation of the pancreas. "Thus, the expression of the histone modifying PRC1 components Bmi1 and Ring1b and the level of the histone modification H2AK119ub were analyzed at two different points in time following cerulein-induced pancreatitis." (PMID 26716510, 2016).
papillary renal cell carcinoma (1 paper, 2023). A rare subtype of renal cell carcinoma, arising from the renal tubular epithelium and showing a papillary growth pattern, which typically manifests with hematuria, flank pain, palpable abdominal mass or nonspecific symptoms, such as fatigue, weight loss or fever. "PRC1 has revealed upper expression in other cancer tissues such as, among others, invasive cervical carcinomas, papillary renal cell carcinoma, pediatric adrenocortical tumour, while yet not being studied in depth as compared to CCNB1, ADAM10 or RACGAP1." (PMID 37438763, 2023).
renal carcinoma (1 paper, 2025). A carcinoma arising from the epithelium of the renal parenchyma or the renal pelvis. "Quantitative real-time PCR analysis of four renal cancer cell lines revealed significantly higher PRC1 levels compared to HK-2 and 293-T cell lines." (PMID 40093809, 2025).
retinoblastoma (1 paper, 2022). A malignant tumor that originates in the nuclear layer of the retina. "Additionally, it has been reported that silencing the expression of Prc1 can inhibit the Wnt/β-catenin signaling pathway, inhibit the proliferation, invasion, and angiogenesis of retinoblastoma cells." (PMID 35393397, 2022).
rheumatoid arthritis (1 paper, 2022). A chronic, systemic autoimmune disorder characterized by inflammation in the synovial membranes and articular surfaces. "Based on the Gene Expression Omnibus (GEO) database, GZMA, PRC1 and TTK were enriched in the innate immune cell-mediated immune response and immune-related biological processes, validating them as potential targets for rheumatoid arthritis (RA) therapy." (PMID 35651940, 2022).
sarcoma (1 paper, 2021). A usually aggressive malignant neoplasm of the soft tissue or bone. "They provide a strong foundation for investigating the utility of BMI1 inhibition in ARMS and should spur further investigations of BMI1 and other PRC1/2 proteins as potential dependencies in RMS and other sarcomas." (PMID 33523558, 2021).
silicosis (1 paper, 2023). Silicosis is a respiratory disease caused by breathing in (inhaling) silica dust. "In the rat model exposed to silica inhalation for 4 weeks, Bub1, Kifc1, Mcm6, and Prc1 were upregulated in the silicosis group, while Cdkn3 was downregulated." (PMID 37278873, 2023).
T cell lymphoma (1 paper, 2017). "Direct binding of MALAT1 to the PRC2 components (EZH2 and SUZ12) was observed in a T cell lymphoma cell line; however, no direct binding of MALAT1 with H3K27me3 and BMI1 (a PRC1 component) was observed." (PMID 28412742, 2017).
thyroid (1 paper, 2025). "Moreover, Amyloid precursor-like protein 2 (APLP2), Ribonucleotide reductase M2 polypeptide (RRM2) and Protein Regulator of cytokinesis 1 (PRC1) are new indicators studied to differentiate thyroid follicular lesions." (PMID 40420140, 2025).
thyroid carcinomas (1 paper, 2019). "TCGA data suggested that the expression levels of TOP2A, TYMS, FEN1, and PRC1 genes were also upregulated in other histological subtypes of thyroid carcinoma." (PMID 30774662, 2019). "Results suggested that the expression levels of hub genes, TOP2A, TYMS, FEN1, and PRC1, were also upregulated in at least one histological subtype of thyroid carcinoma." (PMID 30774662, 2019). "Further survival analysis showed that high expression of TOP2A, TYMS, FEN1, PRC1, or UBE2C gene significantly decreased disease-free survival of patients with other thyroid carcinomas." (PMID 30774662, 2019). "Survival analysis indicated that high expression of TOP2A, TYMS, FEN1, PRC1, or UBE2C gene significantly decreased disease-free survival of patients with other thyroid carcinomas." (PMID 30774662, 2019). "High expression of TOP2A, TYMS, FEN1, PRC1, or UBE2C gene significantly decreased disease-free survival of patients with other thyroid carcinomas." (PMID 30774662, 2019).
vascular malformation (1 paper, 2024). A non-neoplastic disorder that is the result of defects of vascular morphogenesis. "Hence, the discovery that the PRC1 protein CBX7 is activated in CCM provides yet another hint at a cancer-like molecular mechanism involved in vascular malformations." (PMID 39402138, 2024).
viral hepatitis (1 paper, 2020). An acute or chronic inflammation of the liver parenchyma caused by viruses. "DNA hypomethylation of DCAF4L2, CKLF and UBE2C was observed in both NASH-related and viral hepatitis-related HCCs, whereas that of TRIM4, PRC1 and TUBA1B occurred in a NASH-related HCC-specific manner." (PMID 32685988, 2020).
ZIKV infection (1 paper, 2021). "Nevertheless, the high correlation between Prc1 expression, AXL expression, and ZIKV infection make AXL an interesting group 1 candidate marker gene." (PMID 34272257, 2021). "Given the separation of Prc1+ and MFAP2+ populations, we next tested whether these groups were differentially vulnerable to ZIKV infection by multiplexing RNAscope probes against Prc1, MFAP2, and ZIKV." (PMID 34272257, 2021).
cancer (167 papers, 2008 to 2025). A tumor composed of atypical neoplastic, often pleomorphic cells that invade other tissues. "According to the literature, PRC1 is regulated by PLK1-dependent phosphorylation, and inhibition of PLK1 or direct targeting of PRC1 can lead to its aberrant expression, subsequently causing cytokinesis defects and cancer progression." (PMID 41187218, 2025). "Protein regulator of cytokinesis 1 (PRC1) is frequently overexpressed in various cancers and is associated with poor prognosis." (PMID 40034437, 2025). "Recruiting PLK1 to the central spindle during anaphase is necessary for its function in promoting cancer cell proliferation, which is achieved by binding to microtubule-associated protein regulating of cytokinesis (PRC1) located in the spindle." (PMID 40355412, 2025). "Elevated PRC1 expression in these cancers is associated with aggressive clinicopathological features and poor prognosis, suggesting its potential as both a prognostic indicator and a promising cancer therapy target." (PMID 40034437, 2025). "Together, this study supports a model where DNA repair and replication defects amplify the tumorigenic transformation epigenetically induced by PRC1 loss, resulting in genomic instability and cancer progression." (PMID 38746379, 2024). "PRC1 has significant clinical implications, including its distinct expression levels across different cancer stages, association with immune cell infiltration, and correlation with established PDAC markers." (PMID 39409930, 2024). "Together, this study supports a model where DNA repair and replication defects accumulate during the tumorigenic transformation epigenetically induced by PRC1 loss, resulting in genomic instability and cancer progression." (PMID 38888809, 2024). "Cancer development has been closely linked with phase-separated macromolecular condensates, including stress granules, DNA repair condensates, PRC1 condensates, super-enhancer condensates, SPOP/DAXX bodies and PML puncta." (PMID 39358623, 2024). "The catalytic components of PRC1 such as RING1 A or B/BMI1 complex are associated with several cancers and correlate with poor prognosis, thus PRC1 represents an attractive therapeutic target for cancer." (PMID 36881608, 2023). "CBX8, encoding one subunit of PRC1 and involved in cancer and immune cell infiltration, is presented to show the elevated H3K4me3 and H3K27ac on its enhancer in tumor tissues." (PMID 38012744, 2023). "Our study provides novel insights into the involvement of variant PRC1 complex for epigenetic mechanism of cancer malignancies." (PMID 33779563, 2021). "Ring1b is a core subunit of polycomb repressive complex 1 (PRC1) and is essential in several high-risk cancers." (PMID 33608512, 2021). "Dysregulation of PRC1/2 protein members are implicated in tumor initiation and progression in many adult cancers but remain relatively understudied in pediatric cancers." (PMID 33523558, 2021). "PRC1 in HCC tissue is regulated by Wnt3a signaling, exerting an oncogenic effect by promoting cancer proliferation, stemness, metastasis, and tumorigenesis; high expression of PRC1 was associated with early HCC recurrence and poor patient outcome." (PMID 31001331, 2019). "Reports indicated that RYBP is a multifunctional protein, which binds several transcriptional factors and components of polycomb repressive complex 1 (PRC1), and is associated with development, as well as apoptosis and cancer." (PMID 29383875, 2018). "Recent studies suggested that PRC1 genes that play important roles in cancer carry out their functions independently of their association with PRC114,15." (PMID 30139998, 2018). "Both KIF4A and its binding proteins such as PARP-1, BRCA2 and PRC1 have been implicated in multiple types of human cancers." (PMID 28160558, 2017). "This locus lies in intron 14 of the protein regulator of the cytokinesis 1 (PRC1) gene, which encodes the PRC1 protein and is suspected of being strictly regulated in a cancer-specific manner." (PMID 27705907, 2016).